IL4I1 (interleukin 4 induced 1)
Diseases named in the same sentence as IL4I1 in open-access papers (continued):
Sharing a sentence is not in itself a finding about the gene and the disease.
cancer (continued). "The results showed that IL4I1 methylation was downregulated in most types of cancer, including KIRC, UCEC, BRCA, LUSC, THCA, KIRP, and LUAD." (PMID 38691253, 2024). "As a metabolic immune checkpoint protein, interleukin-4-induced gene 1 (IL4I1 orFIG1) has been extensively studied in human cancers and inflammatory diseases." (PMID 39355609, 2024). "We further investigated changes in the IL4I1 gene in pan-cancer samples from TCGA using the cBioPortal." (PMID 38691253, 2024). "The expression profile of IL4I1 at the single-cell level and its potential functional status in pan-cancer were explored through an analysis of CancerSEA." (PMID 38691253, 2024). "The functional enrichment of IL4I1 in cancer was investigated by mapping its protein interaction network using the STRING database." (PMID 38691253, 2024). "Recent data showed that different types of human cancers directly produce IL4I1 to form metabolites that activate aromatic receptors (aryl hydrocarbon receptor [AhR])." (PMID 38691253, 2024). "Using the TIMER2 database, we found that the expression of IL4I1 was positively correlated with the degree of invasion of TAM and cancer-associated fibroblasts (CAF) in pan-cancerous tissues." (PMID 38691253, 2024). "Upon inhibition of IDO1 in cancer patients, the amount of Trp available as a substrate for IL4I1 would likely be replenished." (PMID 36765849, 2023). "It is reported that cancers expressed high levels of IL4I1, inducing the differentiation of Tregs, promoting CD8+ T cell death, recruiting immunosuppressive TAMs and suppressing T cell proliferation and function via the Kyn-AHR axis." (PMID 37434155, 2023). "Interleukin-4-induced-1 (IL4I1), a L-amino acid oxidase, was very recently identified as a novel potential target of cancer treatment." (PMID 37507432, 2023). "TCGA, GTEx, and HPA databases were applied to assess the IL4I1 expression, clinical characteristics, and prognostic value of pan-cancer." (PMID 38250074, 2023). "Recently, we and others discovered another mechanism by which tryptophan metabolism can promote cancer cell survival through IL4i1 and IDO1, namely, via suppression of ferroptosis." (PMID 37196768, 2023). "Most recently, interleukin 4 induced 1 (IL4I1), secreted by professional antigen-presenting cells in various cancer types, was indicated as yet another enzyme capable of producing AhR agonists through metabolism of Trp." (PMID 36765849, 2023). "At last, we did some in-vitro experiments to verify IL4I1 promotion of cancer proliferation and metastasis." (PMID 37434155, 2023). "Recent studies suggested that IL4I1 catalyzed tryptophan into indole-3-pyruvate (I3P) and promoted cancer cell motility and metastasis through." (PMID 37434155, 2023). "To estimate the gene expression profile of IL4I1 in various cancer types, we included 33 types of cancers containing more than three samples in both the normal and the cancer groups." (PMID 37434155, 2023). "recently identified IL4I1 as a major aryl hydrocarbon receptor (AHR)-activating enzyme that promotes AHR-driven cancer cell motility and suppresses adaptive immunity." (PMID 36466837, 2022). "Trp can be metabolized to I3P catalyzed by interleukin 4 induction 1 (IL4i1), a FAD-dependent oxidoreductase that metabolizes AAs and is linked to immune suppression in cancer." (PMID 35280684, 2022). "IL4I1 expression in human cancer is frequent and correlates with poor survival and resistance to immunotherapy." (PMID 36131918, 2022). "IL4I1 is overexpressed in many cancers, including OC, and correlates with increased numbers of immunosuppressive cell TME infiltrates." (PMID 34944851, 2021). "IL-4i1–deficient (IL-4i1−/−) mice displayed increased protection against acute H37Rv, HN878 and chronic HN878 Mt infections, with reduced lung bacterial burdens and altered APC responses compared with wild-type mice." (PMID 34739044, 2021).
cancer (continued). "Further research is needed to elucidate the precise mechanisms through which IL4I1 operates, which may ultimately offer novel strategies for cancer diagnosis and treatment." (PMID 41008831, 2025). "IL4I1 is highly expressed in the majority of malignant tumors." (PMID 41008831, 2025). "Across human cancer types, IL4I1 gene expression associates more strongly with a pan-tissue AhR activation signature compared to that of either IDO1 or TDO, indicating IL4I1-generated metabolites as key AhR activators in cancer." (PMID 39211039, 2024). "Finally, we evaluated the relationship between the levels of IL4I1 methylation and OS in 22 cancer types." (PMID 38691253, 2024). "A more comprehensive understanding of the consequences of IL4I1 expression and its inhibition in cancer is, however, required to determine whether this enzyme indeed constitutes an effective immunotherapeutic target." (PMID 39211039, 2024). "We analyzed the differential expression of IL4I1 in 33 cancers using the TCGA + GTEx database." (PMID 38691253, 2024). "A significant difference in IL4I1 expression was observed between cancer and normal tissues." (PMID 38691253, 2024). "Finally, the in vitro experiments revealed the promotion of IL4I1 on cancer cell proliferation, migration and invasion." (PMID 37434155, 2023). "Recently, IL4I1 has been recognized as a promising target for cancer treatment." (PMID 38250074, 2023). "IL4I1 is expressed by cancer cells in response to IFNγ and TNF-α." (PMID 36834576, 2023). "Latest studies have found that the Interleukin-4-induced-1 (IL4I1) enzyme can also catalyse tryptophan to generate kynurenine and indole metabolites, complementing the tryptophan metabolic pathway and opening up new avenues for cancer treatment." (PMID 37391812, 2023). "Interleukin-4-induced-1 (IL4I1) expression is higher than IDO1 in most cancer types." (PMID 37635168, 2023). "Here, we summarize the recent advances in this field, focusing on IDO1 and IL4i1 in cancer." (PMID 37196768, 2023). "Previous studies have shown that IL4I1 could augment growth vitality of cancer cells and diminish the motility of CD8+ T cells through the I3P-aryl hydrocarbon receptor (AHR) axis." (PMID 38250074, 2023). "The enrichment of CTLA4 and IL4I1 were consistent with their functions in cancer." (PMID 35778697, 2022). "Such interference may be exploited to limit the immunosuppressive effect of IL4I1 in situations in which it is detrimental, such as cancer." (PMID 36131918, 2022). "Given that IL4i1 activates anti-ferroptosis pathways through I3P and possibly other indoles, we speculate that blocking IL4i1-mediated Trp metabolism could be a useful anti-cancer therapeutic strategies." (PMID 35280684, 2022). "Therefore, IL4I1 may be used as a prognostic biomarker or protective factor in numerous types of cancer." (PMID 38691253, 2024). "Therefore, IL4I1 may be a new therapeutic target for the treatment and prognosis of patients with cancer." (PMID 38691253, 2024). "IL4I1 may play a role as promoter of cancer and prognostic indicator in patients." (PMID 38691253, 2024). "Consequently, IL4I1 is considered an immune checkpoint target, and based on our study as well as the role of IL4I1 in immune response in cancer, we hypothesize that IL4I1 and the hydrogen peroxide byproduct also play a role in vaccine response in infants." (PMID 37610205, 2023). "We speculate that while inhibition of IDO1 remains a viable adjuvant therapy for solid tumors, the overlapping effects of IL4i1 must be accounted for, as potentially both enzymes may need to be inhibited at the same time to produce positive effects in cancer therapy." (PMID 37196768, 2023).
cancer (continued). "Therefore, targeting IL4i1 in cancer immunotherapy may represent a promising new strategy to restore cancer immune control." (PMID 37196768, 2023). "Thus, we speculate that an inhibitor of IL4i1 may be a useful anti-cancer drug, as it may sensitize cancer cells to ferroptotic death by blocking IL4i1-mediated amino acid metabolism." (PMID 33646117, 2021). "Interestingly, the production of KYNA may not be limited to just via KP but rather through an alternate TRP metabolism mediated by Interleukin-4-induced gene 1 (IL4I1) in a cancer setting." (PMID 34680327, 2021). "As a secreted enzyme, IL4I1 may represent an easily targetable molecule for cancer immunotherapy." (PMID 31330829, 2019). "Thus, IL4I1 may regulate the balance of effector versus suppressive T cells in inflammatory microenvironments, such as cancer." (PMID 29206151, 2017). "Increasing evidence suggests that the metabolic adaptations of T cells determine their function by reprogramming T-cell metabolism through checkpoints like IDO, IL4I1, and SIRT2, resulting in improved anti-cancer immune efficacy." (PMID 38755125, 2024). "Results indicated high expression of IL4I1, TDO2, NIT2, and IDO1, while IDO2, ADI1, DDC, HPD, BHMT2 exhibited low expression in most cancers." (PMID 38691253, 2024). "IL4I1 acts as the main regulator of Trp/AHR signaling and promotes the immune evasion of several cancer types, underscoring its significance as a key drug target." (PMID 37655051, 2023). "has described, and largely proved, that interleukin 4 (IL‐4)‐induced gene 1 (IL4I1), a secreted enzyme belonging to the L‐amino‐acid oxidase family, was able to promote Aryl‐Hydrocarbon Receptor (AHR)‐driven cancer immunosuppressive ability." (PMID 38117000, 2023). "A recent study has revealed that the L-amino acid oxidase interleukin-4-induced-1 (IL4I1) generates indole metabolites and kynurenic acid, which are agonists of AHR, thereby promoting cancer cell motility and suppressing adaptive immunity." (PMID 36269001, 2022). "What’s more, a recent study demonstrated that IL4I1 is a major aryl hydrocarbon receptor (AHR)-activating enzyme and endowed cancer cells with the capacity of migration and metastasis." (PMID 34134578, 2021). "In conclusion, IL4I1, ITGB7, and FUT7 were identified as the hub genes between two hallmarks in cancer, glucose metabolism, and cancer-specific immunity via comprehensive bioinformatic analysis." (PMID 34134578, 2021). "Based on the results that IL4I1 develops a metabolic resistance mechanism against ICB and/or IDO1 by activating AHR, this research provided a new and crucial avenue for cancer therapy." (PMID 33692337, 2021). "Most important, IL4I1, ITGB7, and FUT7 were revealed in both the cancer-immune gene set and glucose metabolic gene set." (PMID 34134578, 2021). "While there is currently no indication for a role of these metabolites in cancer development or immunosuppression, these findings suggest considerable activity of IL4I1 in these patients." (PMID 39211039, 2024). "This provides a novel link between IL4i1- and IDO1-positive TMEs and cancer cell survival." (PMID 37196768, 2023). "Despite being recognized as a key immunoinhibitory enzyme in various cancers, the targetable value of IL4I1 in sensitizing the immunotherapy is still not clear." (PMID 37655051, 2023). "IL4I1, ITGB7, and FUT7 may be the hub genes that link glucose metabolism, and cancer-specific immunity." (PMID 34134578, 2021). "For the moment, no studies correlating IL4I1 expression with that of the other immunosuppressive enzymes have been done in human cancers." (PMID 31330829, 2019).
cancer (continued). "On the contrary, in patients with non-hematological tumors infiltrated by macrophages, IL4I1 is expected to negatively affect the evolution of the cancer due to its suppressive effect on the T-cell response." (PMID 31330829, 2019). "In fact, many scRNAseq data sets show overlapping patterns of myeloid IL4i1 and IDO1 expression in the TME raising the possibility that (i) this is a universal response in the chronic inflammation of cancer and (ii) that multiple factors may control the expression of both enzymes." (PMID 37196768, 2023). "However, we believe, on the contrary, that the absence of IL4I1 is favorable in situations of chronic antigen exposure, including cancer." (PMID 33343572, 2020). "Furthermore, we show that IL4I1, IDO1, or AHR high expression correlates with poorer survival of LGG patients, and that high IL4I1 expression also correlates with poorer outcome in GBM patients, confirming the clinical relevance of this pathway in these cancers." (PMID 38937431, 2024). "However, currently, there is no comprehensive study on the role of IL4I1 in the pan-cancer setting." (PMID 38691253, 2024). "Furthermore, we show that IL4I1, IDO1, or AHR high expression correlate with poorer survival of LGG patients, and that high IL4I1 expression also correlates with poorer outcome in GBM patients, confirming the clinical relevance of this pathway in these cancers." (PMID 37986881, 2023). "IDO1 inhibitors were developed and tested in numerous cancer clinical settings without knowledge of the overlapping pathways regulated by IL4i1, and without knowing that both IDO1 and IL4i1 control redox stress responses." (PMID 37196768, 2023). "Because IDO inhibitors do not block IL4I1, these findings may explain the failure of a phase III clinical trial combining immune checkpoint blockade with IDO1 inhibition for cancer treatment." (PMID 36269001, 2022). "Given that the activity of IL4I1 is independent of the KP and can limit antitumor immune cell response, inhibiting the formation of KYNA metabolite either via the KP or through IL4I1 gene reaction may be necessary to block the activation of AhR in cancer." (PMID 34680327, 2021).
infection (9 papers, 2013 to 2024). The state of being infected such as from the introduction of a foreign agent such as serum, vaccine, antigenic substance or organism. "IL-4i1 deficiency in BMDMs resulted in a decreasing trend of intracellular mycobacterial growth at 1 and 3 days after infection with virulent H37Rv Mtb strain." (PMID 34739044, 2021). "Here, we describe the differentiation of CD8 T cells from the endogenous repertoire and from the transgenic P14 clone in IL4I1-competent and IL4I1-deficient mice after in vivo priming by an acutely cleared infection with LCMV." (PMID 33343572, 2020). "Thus, the diminution of plasma IFNγ in mice challenged with bacteria and IL4I1 probably reflects the reduced inflammation associated with the control of the infection." (PMID 23355881, 2013). "IL4I1 plays an important role in the body’s defense against infection, regulation of immune homeostasis and injury response." (PMID 38140587, 2023). "To determine the role of IL-4i1 in macrophage polarization in vivo, 12 days after infection, we used flow cytometry to determine the number of “M1-like” restrictive and “M2-like” permissive macrophages infiltrating the lungs of WT and IL-4i1−/− mice." (PMID 34739044, 2021). "In conclusion, our findings suggested that, in early infection, increased expression of IL-4i1 regulates APC-mediated immunity." (PMID 34739044, 2021). "Taken together, the deletion of the Il4i1 gene rendered mice more protected against Mtb during the chronic stage of infection, with consistent effects on mycobacterial burdens and diminished tissue damage." (PMID 34739044, 2021). "We evaluated IL-4i1 deletion in macrophages and mice on infection with virulent H37Rv and W-Beijing lineage hypervirulent HN878 Mycobacterium tuberculosis (Mtb) strains." (PMID 34739044, 2021). "Five days post-infection, the P14 cells detected in WT and IL4I1-/- mice expressed similar levels of the activation marker CD44, but their expansion was markedly lower in IL4I1-/- mice." (PMID 33343572, 2020). "IL4I1 reached its peak expression (458× induction) in the cecum of newly hatched chickens 4 days post-infection and remained upregulated for an additional 10 days." (PMID 32404145, 2020). "We evaluated the role of IL4I1 in the early steps of the CD8+ T-cell response using the LCMV acute resolutive infection model." (PMID 33343572, 2020). "Three, four and five days post-infection, IL4I1 exhibited 400–500 fold induction, which makes this gene one of the most inducible gene in the chicken cecum after S. Enteritidis infection." (PMID 32404145, 2020). "In this study we have shown that IL4I1 is one of the most inducible genes in the chicken cecum after infection with S. Enteritidis." (PMID 32404145, 2020). "IL4I1 expression has also been reported in alveolar type II cells during infection by the mold Aspergillus fumigatus and a monocytic macrophage cell line infected with Candida albicans, although its role in the antifungal response was not established." (PMID 31330829, 2019). "Indeed, the il4i1 gene presented the greatest level of induction after infection in the liver samples from the resistant family." (PMID 39712009, 2024). "Moreover, the addition of IL4I1 to hMDM before infection with the SARS-CoV-2 LVS significantly decreased entry of the virus." (PMID 36131918, 2022). "IL-4i1 deficiency led to improved protection of mice against acute H37Rv and acute/chronic HN878 Mtb infection, as denoted by a reduced mycobacterial burden for both strains and slightly reduced histopathology at later stages of infection." (PMID 34739044, 2021). "Unexpectedly, we show that IL4I1 accelerates the expansion of functional effector CD8 T cells during the first several days after infection and increases the average affinity of the elicited repertoire, supporting more efficient LCMV clearance in WT mice than IL4I1-deficient mice." (PMID 33343572, 2020). "At mRNA level, IL4I1 was maximally expressed in the cecum 4 days after the infection." (PMID 32404145, 2020).